TBK1 (TANK binding kinase 1)
Diseases named in the same sentence as TBK1 in open-access papers (continued):
Sharing a sentence is not in itself a finding about the gene and the disease.
infection (continued). "TBK1–/– MEFs confirmed the specificity of the used antibody raised against p-TBK1S172 and, at later time points post-infection, we observed that the active form of TBK1 accumulates very close to the Golgi apparatus, at the centrosome." (PMID 27538435, 2016). "Upon infection with viral DNA or RNA, TRIM9 short isoform undergoes Lys-63-linked auto-polyubiquitination and recruits GSK3β to TBK1, resulting in the activation of the IRF3 signaling pathway." (PMID 27667714, 2016). "Following infection with Sendai virus, leading to RLR activation, an increase in the association of TBK1 with OPTN was detected and p-TBK1S172 was found in complex with OPTN in the Golgi-enriched fraction." (PMID 27538435, 2016). "Of note, mitochondrial localization of active TBK1 has only been reported in response to infection by DNA viruses." (PMID 25923723, 2015). "Western blot analysis demonstrated that MVA-N1L infection triggered reduced levels of activation of p-TBK1 and p-IRF3 at 4 and 8 h post-infection when compared with MVA." (PMID 24743339, 2014). "We now show that TBK1 is ubiquitinated on residues K69, K154, and K372 in response to infection with RNA virus." (PMID 23028469, 2012). "In summary, we identified sites of TBK1 ubiquitination in response to infection with RNA viruses and proposed a mechanism for assembly of a RLR-induced molecular complex responsible for IRF3 signal propagation." (PMID 23028469, 2012). "The real time qRT-PCR verification performed for the NFKB1 and the TBK1 genes, both of which are represented in the infection signature panel, supports the reliability of this method for the detection of a gene infection signature for BTB." (PMID 17974019, 2007). "Similarly, TANK-binding kinase 1 (TBK-1) was demonstrated to phosphorylate p62 at the same site during the infection of macrophages with M. tuberculosis." (PMID 40853005, 2025). "We used an acute 1-hour infection to directly evaluate the TBK1/IKKε effect on cell death responses and separate this direct control of cell death from any later, transcription-dependent roles of TBK1/IKKε in anti-Listeria defenses." (PMID 40053580, 2025). "TBK1 and IKKε play a central role in activating proinflammatory cytokine secretion, antiviral immunity, transcriptional responses, and autophagy, all essential to counteract infection and tissue damage and for cells to return to homeostasis." (PMID 40053580, 2025). "To ascertain whether Frk phosphorylates TBK1 during infection and to elucidate the mechanism, we infected RAW264.7 cells with VSV and HSV-1." (PMID 40012791, 2025). "Finally, we demonstrated that the LIT domain is functionally required for TBK1-mediated suppression of MCPyV replication during early infection." (PMID 41277846, 2025). "Infection with NH/P68 also caused down-regulation of IFNAR1 and NLRP3 receptors, MYD88 adaptor proteins, as well as other molecules involved in modulating receptor signaling pathways (JUN, PELI1, TBK1, and TICAM2)." (PMID 40530033, 2025). "Furthermore, we elucidated the mechanism by which Frk phosphorylates TBK1 during infection and the role of Frk in IFN-β production." (PMID 40012791, 2025). "Moreover, deletion of TBK1 from porcine cells led to an increase in PSaV titres, emphasizing its role in regulating PSaV infection." (PMID 38400023, 2024). "Consequently, the association of TBK1 and IRF3, which plays a vital role in type I interferon (IFN-I) induction, was blocked by EBOV trVLPs infection." (PMID 38285487, 2024). "For this purpose, we analyzed the phosphorylation status of several of the main proteins of this pathway (STING, IRF3, and TBK1) at different post-infection times (4, 8, and 16 hpi) during infection with the recombinant virus compared to the parental Arm/07/CBM/c2 virus." (PMID 38675789, 2024).
infection (continued). "Upon infection by RNA or DNA viruses, activated TBK1 and IKKε/i phosphorylate IRF3 at specific serine residues; and IRF3 then undergoes nuclear translocation to initiate the transcription of type I IFN by binding to specific regulatory elements known as IFN-stimulated response elements (ISREs)." (PMID 38396775, 2024). "In order to assess whether cleaved TBK1 is also targeted for proteasomal degradation during the course of infection, we infected LLC-PK1 cells at high MOI (5 TCID50/cell) in the presence or absence of zVAD-FMK or MG132." (PMID 38400023, 2024). "To assess whether the decreased expression of TBK1 was cell-type-specific, we established PSaV infection in the IPEC-J2 cells, an enterocyte cell line originally derived from the jejunum of a neonatal piglet." (PMID 38400023, 2024). "However, the microscopy images of OPTN KO and TBK1 KO cells infected with HSV-1 revealed an unexpectedly higher spread of infection in OPTN KO cells compared to the TBK1 KO cells." (PMID 38019030, 2023). "Although the infection levels differed in OPTN and TBK1 deficient cells, in this series of experiments, we aimed to evaluate whether TBK1 and OPTN work collectively to trigger an IFN response against HSV-1." (PMID 38019030, 2023). "ASFV-Δ110-9L/505-7R infection blocked autophagic degradation of TBK1." (PMID 37162350, 2023). "However, activated TBK1 (pS172-TBK1) was higher in Mk2-rescued MEFs after infection in comparison to Mk2-/- MEFs." (PMID 37771590, 2023). "Indeed, our results showed that PKR was required for TBK1 induction in response to infection by HSV." (PMID 37764935, 2023). "Of note, Co-IP results showed that HSV1-GFP infection markedly enhanced the association of TBK1 and PTK2B, but it had no apparent effect on enhancing the STING-PTK2B interaction." (PMID 37989995, 2023). "As iron metabolism is dynamically altered during infection, TBK1 and BACH1 may contribute to immune responses as well as EMT by altering iron metabolism." (PMID 36009179, 2022). "Moreover, NSP5 and N suppressed IFN expression induced by infection of Sendai virus or transfection of a synthetic mimic of dsRNA, poly (I:C), inhibiting TBK1 and IRF3 phosphorylation, and restraining the nuclear translocalization of IRF3." (PMID 35075101, 2022). "Our data on gene expression analysis in infected cGAS and TBK1 knockout cell lines identified a number of shared up- and down-regulated genes which collectively might contribute to establishment of infection resistance." (PMID 36405710, 2022). "We next re-analyzed TBK1 activation upon infection using control and gal8 KO cells." (PMID 35857795, 2022). "Thus, activation of TBK1 plays a crucial role in producing type I IFN as an antiviral innate immune response following infection." (PMID 35632751, 2022). "Furthermore, the timing of activation of TBK1 and its recruitment to the penetration site within 20 min of infection coincides with the detection of the viral membrane damage by galectins." (PMID 35857795, 2022). "Therefore, to specifically address the contribution of TBK1 to IRF1 induction we performed siRNA-mediated knockdown of TBK1 in MDMs prior to infection with HMPV." (PMID 34248923, 2021). "Additionally, arginine methylation of hnRNPA1/B2 triggers its export to the cytoplasm where it activates TBK1/IRF3 signaling following infection with a DNA virus." (PMID 34305890, 2021). "As expected, infection with MAB induced phosphorylation of TBK1 in both BMDMs and MH-S cells." (PMID 34777348, 2021). "Upon SeV or EMCV infection, macrophages or MEFs with the deficiency of USP18 showed impaired phosphorylation of TBK1 and IRF3, expression of Ifnb and Ccl5, and production of IFN-β, indicating that USP18 plays a positive role in regulating viral-induced type-I interferon response." (PMID 34016972, 2021). "Besides pathogen infection, proinflammatory cytokines such as tumor necrosis factor α (TNFα) also produces TBK1 activation." (PMID 33193441, 2020).
infection (continued). "Because TBK1 has been implicated in autophagy induction, whereas IRF3 acts as a transcription factor to induce type I IFNs downstream of STING, we investigated the role of these proteins in the context of an in vivo infection with HSV-1." (PMID 32636381, 2020). "TBK1 mRNA levels were significantly decreased at 24 h and 36 h post infection (hpi)." (PMID 32486349, 2020). "In addition, a study showed that the TBK1 from large yellow croaker (L. crocea) can be regulated by Nrdp1, an E3 ubiquitin ligase, and was involved in the immune defense against the pathogen infection." (PMID 28714877, 2017). "Thus, this RNA virus prevents OPTN from activating TBK1 as part of a strategy to modulate the innate immune response to facilitate its replication after infection." (PMID 27538435, 2016). "Similarly, the infection of HeLa cells with Sendai virus led to a detection of the active form of TBK1 at the Golgi apparatus." (PMID 27538435, 2016). "Indeed, it has been reported that MTB induces IFN production during macrophage infection via the activation of a STING/TBK1/IRF3 signaling axis." (PMID 26654095, 2015). "At later times of infection, several TBK1-related mechanisms could be involved in the termination of IFN activation." (PMID 25923723, 2015). "However, the interaction between DYRK2 and TBK1 became evident 8 hours after infection, gradually increased between 8 and 12 hours after stimulation, and then completely disappeared." (PMID 26407194, 2015). "Thus, mutation of the K69 or K154 TBK1 ubiquitin acceptor sites impairs antiviral activity and IFN production in response to infection." (PMID 23028469, 2012). "In addition, tbk1−/− MEFs reconstituted with either K69R or K154R TBK1 produce less IFNβ following infection with Sendai virus than cells reconstituted with wild type or K372R TBK1." (PMID 23028469, 2012). "Therefore a tripartite complex containing TBK1/IRF3/PLP2 would exist in cells after infection of MHV-A59." (PMID 21364999, 2011). "There was little change in the level of TBK1 protein during infection." (PMID 21677781, 2011). "However, upon infection of cells that express the NLRP3 inflammasome, (e.g., macrophages), with pathogens that activate this pathway (e.g., Listeria monocytogenes), TBK1/IKKε-deficient cells die rapidly, prematurely, and exclusively by enhanced NLRP3-driven pyroptosis." (PMID 40053580, 2025). "However, the levels of TBK1 and p62 were recovered at 16 h post infection." (PMID 39339967, 2024). "Then, we examined whether Tyr phosphorylation of TBK1 occurred upon HSV1-GFP infection." (PMID 37989995, 2023). "Indeed, we found that inhibition of TBK1 not only results in significant elevations in vesicle-based CVB egress and increases in overall infection, in a mouse model of viral pancreatitis, blocking TBK1 also exacerbates pancreatic destruction and leads to a rise in pancreatic and serum viral titers." (PMID 40396014, 2022). "Moreover, in the current study, western blot results showed that expression of gB protein which is essential for attachment and penetration of free virions, cell fusion and infection transmission was significantly decreased in TBK1 overexpressed cells, implying the role of TBK1 during DEV infection." (PMID 35632751, 2022). "Notably, the binding of SRA to TBK1 in HEK293T cells increased after VSV or HSV-1 infection." (PMID 36342281, 2022). "Infection could be maintained over a period of weeks by inhibiting the innate immune response with inhibitors of the Janus kinase (JAK) family or the signaling intermediate TANK binding kinase 1 (TBK1)." (PMID 34360991, 2021). "Therefore, we hypothesized that T. gondii may take advantage of this interaction between PI3K/AKT signalling and TBK1/IRF3 pathway while its infection period." (PMID 34464509, 2021). "We found that SAFA could colocalize with p-TBK1 under SFTSV infection." (PMID 34788350, 2021).
infection (continued). "The homologs of STING in invertebrate are postulated to loss the function to induce innate immune response against infection for the lack of a carboxy-terminal tail (CTT) domain which is the essential domain for mammalian STING to recruit the critical downstream TBK1 and IRF3 signaling components." (PMID 34168656, 2021). "We also observed that MVA infection resulted in much higher levels of phosphorylation of TBK1 than WT VAC, indicating that WT VAC might encode inhibitor(s) that interfere with phosphorylation of TBK1 and IRF3." (PMID 24743339, 2014). "Given that both SVCV-P and IRF3 independently possess LLPS capabilities, we are prompted to explore the interplay between TBK1 phase separation events driven by SVCV-P and those triggered by IRF3 during a genuine SVCV infection." (PMID 41363845, 2026). "The activation of TBK1 and IRF3 is conventionally induced by the canonical RIG-I pathway later in infection." (PMID 39601535, 2025). "The transcript and protein levels of IFN-α, IFN-β, RIG-I, MDA5, MAVS, TRAF3, TBK1, and IRF3 in the PRRSV-ICs-infected cell group were significantly diminished at 12 h and 24 h post-infection compared to those in the PRRSV-PNI-infected cell group." (PMID 41012704, 2025). "For example, DDX5 and DDX19A promote TBK1 degradation, preventing the interaction of TBK1 with IRF3 and resulting in decreased IRF3 activation and IFN production during spring viremia of carp virus (SVCV) and EMCV infection, respectively." (PMID 39620586, 2025). "The expression levels of TBK1 and IRF3 were significantly increased in TRIM38 overexpressing cells after infection with ZIKV." (PMID 40006954, 2025). "We found here that in a macrophage infection model with the RIPK1-activating pathogen, Y. pseudotuberculosis, the cell death is RIPK1 driven, yet TBK1/IKKε inhibition also sensitizes cells to enhance secondary NLRP3-dependent caspase-1 activation." (PMID 40053580, 2025). "Consistently, phosphorylation of TBK1, MITA and IRF3 was markedly increased following infection with VACVOPG147/3A compared to wild-type VACV in THP-1 cells." (PMID 40498864, 2025). "At 2, 6, and 12 h post-infection (hpi), the transcriptional levels of key genes of cGAS/STING signaling pathway, including cGAS, STING, TBK1, IRF3, IRF7, and IFN-β were evaluated." (PMID 39601590, 2025). "The results showed a significant increase in the phosphorylation of STING, TBK1 and IRF3 upon PRV-ΔUS1 infection compared to PRV-WT." (PMID 41196926, 2025). "DSTYK knockdown also inhibited the phosphorylation of TBK1, IRF3, STING, P65 and IκBα following pDNA transfection and infection with vaccinia virus (VACV; a DNA virus; Fig. EV3A,B,D,E,G); however, SeV-induced responses were not altered (Fig. EV3C,F,H)." (PMID 39979465, 2025). "Finally, while our study has demonstrated that TBK1 is targeted during late stages of PSaV infection, it is important to acknowledge that the virus may exhibit additional mechanisms to circumvent the innate immune response earlier in the infection process." (PMID 38400023, 2024). "Infection with the cardiotropic viruses CVB3 and EMCV markedly increased oxidation of the free thiol group on TBK1 in both human and mouse cardiomyocytes." (PMID 38664417, 2024). "TBK1 levels were reduced in both DMSO- and zVAD-FMK-treated cells upon infection, which is in accordance with our previous observations." (PMID 38400023, 2024). "WT, Rig-I/Mda5 KO, IPS1 KO, and Tbk1/Ikk-i KO MEFs were infected with 1 MOI HAZV, and Ifnb, Il6 and Tnf expression was measured at 24 h after infection." (PMID 39348382, 2024). "TBK1, IRF3 and IκBα phosphorylation were all reduced at 2 and 4 h post infection (h p.i.), confirming that HOIP is required for the complete activation of both IRF3 and NF-κB pathways downstream of RIG-I signalling." (PMID 38001254, 2024).
infection (continued). "To investigate the TBK1 protein levels during infection, we infected LLC-PK1 cells with a high multiplicity of infection (MOI) of PSaV (5 TCID50/cell) and collected samples at different time points post-infection (pi)." (PMID 38400023, 2024). "Moreover, TBK1 may hold important pro-viral roles earlier during infection." (PMID 38400023, 2024). "Our data suggest that the cGAS/STING/TBK1 pathway promotes both an IFN-I response and viral IE gene expression following infection of THP1 monocytes, at least in the presence of VPA." (PMID 38932169, 2024). "Next, we conducted immunoblotting assays and found that PTK2B knockdown reduced the levels of phosphorylated STING, TBK1 and IRF3 induced by infection with HSV1-GFP." (PMID 37989995, 2023). "Given our collected data and the cumulative insights from previous research, we anticipated observing comparable infection rates in both OPTN and TBK1 KO cells." (PMID 38019030, 2023). "Consistently, we found that Ptk2b knockout decreased the levels of phosphorylated TBK1 and IRF3 induced by HSV1-GFP or VSVΔM51-GFP infection." (PMID 37989995, 2023). "As upstream signalling molecules of IFN-β production, TBK1, IRF3 and P65 displayed higher phosphorylation in CDK5 knockdown cells after infection with VSV." (PMID 37332205, 2023). "Compared with ASFV-WT infection, ASFV-Δ110-9L/505-7R infection significantly blocked Tbk1 reduction at 24 hpi." (PMID 37162350, 2023). "Immunoblotting results demonstrated that similar to the activation of TBK1 and IRF3, the activation of PTK2B was enhanced upon HSV1-GFP infection in a time-dependent manner." (PMID 37989995, 2023). "In vitro, our studies showed that the phosphorylation of TBK1 and IRF3 in RD cells increased at the early stage and then decreased later after EV-A71 infection, suggesting that the antiviral response was weakened." (PMID 36626364, 2023). "In our study, overexpression or inhibition of IFI6 upregulated IRF7 expression and downregulated TBK1, LGP2, IFN-α, and IFN-γ expression after infection with ARV." (PMID 38033564, 2023). "Consistently, PTK2B overexpression not only augmented the levels of phosphorylated STING, TBK1 and IRF3 induced by HSV1-GFP infection but also increased the levels of phosphorylated TBK1 and IRF3 induced by VSVΔM51-GFP infection." (PMID 37989995, 2023). "Infection of THP1 monocytes resulted in prominent type I IFN induction, as expected, which was found completely dependent on TBK1 and IKKε." (PMID 36936901, 2023). "The phosphorylation modifications of TBK1 and IRF-3 play important roles in the cellular response to infection, inflammation, and other stressful stimuli." (PMID 37515271, 2023). "qRT-PCR assay showed that eight antiviral-related mRNA including IRF3, IRF7, IKKβ, TBK1, IFIT1, IFI44, MX1 and ISG15 displayed significantly stronger and quicker response at early infection under 20 °C." (PMID 37627029, 2023). "During early stages of infection, IFI16 interacts with the viral DNA directly through its HIN domain which in turn enhances cGAS-mediated cGAMP production and TBK1 recruitment to STING." (PMID 36680267, 2023). "Immunoblotting showed that IAV infection induced phosphorylation of both NF-κB p65 and TBK1 and ultimately the production of type-I IFN that was detected in the supernatants of infected NK cells 24 h post-infection." (PMID 37569596, 2023). "Consistent results were obtained when PTK2B and wild-type TBK1 or its mutants were co-expressed in TBK1 knockout MEF cells, followed by HSV1-GFP infection." (PMID 37989995, 2023). "Phosphorylated and total levels of TBK1 and STING remained unchanged between WT and ΔUL138STOP infections." (PMID 37289831, 2023). "We observed that infection with VSV and SEV increased TBK1 phosphorylation, IRF3 phosphorylation, and IRF7 phosphorylation in NSP9-overexpressed L929 cells compared to control vector-overexpressed cells." (PMID 37854611, 2023).